PPM1K (protein phosphatase, Mg2+/Mn2+ dependent 1K)
Description:
Serine/threonine-protein phosphatase component of macronutrients metabolism. Forms a functional kinase and phosphatase pair with BCKDK, serving as a metabolic regulatory node that coordinates branched-chain amino acids (BCAAs) with glucose and lipid metabolism via two distinct phosphoprotein targets: mitochondrial BCKDHA subunit of the branched-chain alpha-ketoacid dehydrogenase (BCKDH) complex and cytosolic ACLY, a lipogenic enzyme of Krebs cycle. At high levels of branched-chain ketoacids, dephosphorylates and activates mitochondrial BCKDH complex, a multisubunit complex consisting of three multimeric components each involved in different steps of BCAA catabolism: E1 composed of BCKDHA and BCKDHB, E2 core composed of DBT monomers, and E3 composed of DLD monomers. Tightly associates with the E2 component of BCKDH complex and dephosphorylates BCKDHA on Ser-337. Regulates the reversible phosphorylation of ACLY in response to changes in cellular carbohydrate abundance such as occurs during fasting to feeding metabolic transition. At fasting state, appears to dephosphorylate ACLY on Ser-455 and inactivate it. Refeeding stimulates MLXIPL/ChREBP transcription factor, leading to increased BCKDK to PPM1K expression ratio, phosphorylation and activation of ACLY that ultimately results in the generation of malonyl-CoA and oxaloacetate immediate substrates of de novo lipogenesis and gluconeogenesis, respectively. Recognizes phosphosites having SxS or RxxS motifs and strictly depends on Mn(2+) ions for the phosphatase activity. Regulates Ca(2+)-induced opening of mitochondrial transition pore and apoptotic cell death.
Synonyms: BCKDH; BDP; PTMP; PP2CM; DKFZp761G058; PP2Ckappa; hPTMP; MSUDMV; UG0882E07
Tractability: Small molecule: it has a high-quality binding pocket. PROTAC: ubiquitination databases record sites on it; its protein half-life has been measured.
Gene: Protein-coding gene on chromosome 4 (88,257,620 to 88,284,769, reverse strand). Ensembl gene ENSG00000163644.
Subcellular location: Mitochondrion matrix
Subcellular location (Human Protein Atlas): Mitochondria
Pathways (Reactome):
Disease: H139Hfs13* PPM1K causes a mild variant of MSUD
Metabolism: Branched-chain amino acid catabolism
Gene Ontology:
Molecular function: [3-methyl-2-oxobutanoate dehydrogenase (lipoamide)]-phosphatase activity; manganese ion binding; protein binding; protein serine/threonine phosphatase activity; cation binding
Biological process: branched-chain amino acid catabolic process; regulation of intracellular signal transduction; positive regulation of amino acid metabolic process; regulation of mitochondrial membrane permeability involved in apoptotic process
Cellular component: mitochondrial matrix; mitochondrion
Genetic constraint (gnomAD): Loss-of-function variants: 17 observed, 31.14 expected, observed/expected ratio (o/e) 0.55, 90% interval 0.37 to 0.82. The upper end of that interval is the gene's LOEUF score, 0.82, which puts it in group 3 of 6, group 1 being the genes least tolerant of losing a copy. Missense variants: 350 observed, 468.66 expected, observed/expected ratio (o/e) 0.75, 90% interval 0.68 to 0.82. Synonymous variants: 156 observed, 168.31 expected, observed/expected ratio (o/e) 0.93, 90% interval 0.81 to 1.06.
Gene-disease validity (ClinGen):
ClinGen rates the evidence that PPM1K causes each of these diseases.
maple syrup urine disease, mild variant (autosomal recessive): Moderate.
Homologues: Orthologues: chimpanzee PPM1K (100% identical), macaque PPM1K (99% identical), dog PPM1K (95% identical), guinea pig PPM1K (95% identical), rabbit PPM1K (95% identical), pig PPM1K (92% identical), rat Ppm1k (91% identical), mouse Ppm1k (90% identical), tropical clawed frog ppm1k (74% identical), zebrafish ppm1kb (68% identical), zebrafish ppm1ka (60% identical), Drosophila melanogaster CG10376 (27% identical), and 1 more. Paralogues in human: PPM1L (30% identical), PPM1E (27% identical), PPM1F (26% identical), PPM1A (24% identical), PPM1B (24% identical), PPM1G (23% identical), PPM1N (23% identical), ILKAP (22% identical), PPM1H (22% identical), PDP1 (21% identical), PPM1J (21% identical), PPM1M (21% identical), and 4 more.